R3HCC1L (R3H domain and coiled-coil containing 1 like)
Synonyms: C10orf28; GIDRP88; PSORT; GIDRP86
Tractability: PROTAC: ubiquitination databases record sites on it.
Gene: Protein-coding gene on chromosome 10 (98,134,608 to 98,245,624, forward strand). Ensembl gene ENSG00000166024.
Subcellular location (Human Protein Atlas): Nuclear speckles; Nucleoplasm
Gene Ontology:
Molecular function: protein binding
Cellular component: exon-exon junction complex
Genetic constraint (gnomAD): Loss-of-function variants: 50 observed, 62.05 expected, observed/expected ratio (o/e) 0.81, 90% interval 0.64 to 1.02. The upper end of that interval is the gene's LOEUF score, 1.02, which puts it in group 4 of 6, group 1 being the genes least tolerant of losing a copy. Missense variants: 963 observed, 981.66 expected, observed/expected ratio (o/e) 0.98, 90% interval 0.93 to 1.03. Synonymous variants: 320 observed, 332.76 expected, observed/expected ratio (o/e) 0.96, 90% interval 0.88 to 1.05.
Homologues: Orthologues: chimpanzee R3HCC1L (98% identical), macaque R3HCC1L (93% identical), dog R3HCC1L (76% identical), rabbit R3HCC1L (70% identical), guinea pig R3HCC1L (68% identical), mouse R3hcc1l (64% identical), rat R3hcc1l (62% identical), tropical clawed frog r3hcc1l (30% identical), zebrafish r3hcc1l (20% identical), Drosophila melanogaster CG2162 (17% identical), Caenorhabditis elegans F09C8.2 (10% identical). Paralogues in human: R3HCC1 (13% identical).
Diseases named in the same sentence as R3HCC1L in open-access papers:
R3HCC1L is named in the same sentence as 1 disease in open-access papers, as found by Europe PMC text mining. Sharing a sentence is not in itself a finding about the gene and the disease. The quoted sentences say what the papers report.
tumor (1 paper, 2022). "The analysis of the transposon integration sites identified several candidate genes, of which Man1a1, Pkp4, Rab10, Rasa1, Trps1, Vps26a, Xpnpep3 and Znf326 accelerated tumor growth, whereas the silencing of R3hcc1l reduced tumor growth." (PMID 36497409, 2022).